CD4 (CD4 molecule)
Diseases named in the same sentence as CD4 in open-access papers (continued):
Sharing a sentence is not in itself a finding about the gene and the disease.
anemia (continued). "We found that shedding CFV ≥ 50 copies/mL in breast milk was positively associated with anemia, mild SCM, severe SCM, detectable CAV, low CD4 count and unsuppressed plasma viral load." (PMID 31689745, 2019). "HIV positive patients with CD4 T-cell count < 200 cells had the highest prevalence of anaemia (73.2%) that approached significance (P = 0.05) when compared to their counterparts." (PMID 31752719, 2019). "Chinese HIV patients especially with TB, PM infection and low CD4 level should be routinely detected for anaemia to improve therapy." (PMID 30816082, 2019). "Among participants free of anemia at the baseline, the development of microcytic anemia post-HAART initiation was rare and inversely associated with CD4 cell count and treatment with nevirapine-based HAART." (PMID 30935133, 2019). "The prevalence of mild anaemia and of moderate anaemia showed an increasing trend with decreasing CD4 counts." (PMID 30816082, 2019). "More so, we observed higher odds of anemia in HIV infection in those with CD4+ T-cell count < 200 cells/mm3." (PMID 31703562, 2019). "So periodic screening of anemia, a routine checkup of nutritional status, CD4 count and examination for intestinal parasite are essential." (PMID 31596865, 2019). "A 100% anemia was observed in the category of HIV infected subjects with CD4+ T-Cell count of < 200 cell/mm3." (PMID 31703562, 2019). "Although HAART is capable of reducing the incidence of anemia through enhancing CD4 cell count and suppressing viral duplication, it can also cause anemia." (PMID 31801471, 2019). "The prevalence of IPIs was associated significantly with habit of washing hands before meal, eating uncooked vegetables, taking anti-parasite, anemia, CD4 count and stool consistency." (PMID 31029088, 2019). "After univariable analysis, female sex, lower peak CD4 counts, lower current CD4 counts, anemia, and shorter time infected with HIV-1 were all significantly associated with higher log10 of viral load." (PMID 30866830, 2019). "Anemia was more in participants who had CD4 less than 200 cells/ μL and intestinal parasitic infection were more in those participants." (PMID 31029088, 2019). "Chinese HIV patients especially with PM or TB infection and low CD4 level should be routinely detected for anaemia to improve treatment." (PMID 30816082, 2019). "HIV patients with CD4 cell count < 200 cells/μl before ART initiation had higher prevalence of anemia (49.4%, p < 0.001)." (PMID 29568529, 2018). "Our analysis of the BM microenvironment that supports erythropoiesis has for the first time demonstrated that anemia in murine models of VL represents an aspect of CD4+ T cell mediated immunopathology." (PMID 30619317, 2018). "The frequency and severity of these hematological manifestations increased with the decline in CD4 counts with anemia being the most common hematologic abnormality in HIV patients and is associated with disease progression and decreased survival." (PMID 29568529, 2018). "CD4+ T cell count < 500 cells/mm3 and/or WHO clinical stages, and anemia were found to be significantly associated with the three HIV RNA categories." (PMID 30064395, 2018). "Our findings support the recommendation for early initiation of ART and suggest close monitoring for OIs among patients recently started on ART, with low CD4 cell count, high viral load and anemia." (PMID 30383836, 2018). "By multivariable analysis, factors that remained significantly associated with mortality were age, non-HIV related cancer, cardiovascular disease, decreased eGFR, cirrhosis, anemia, low BMI, and CD4 cell count." (PMID 29672628, 2018). "Low CD4 count, WHO clinical stage III&IV, OIs and low level of BMI were found to have significant association with the occurrence of anemia among HIV infected adult Individuals." (PMID 30459953, 2018).
anemia (continued). "Median CD4 count was 227 cells per μL (IQR 79–436), 748 (29%) of 2574 patients had a CD4 count of less than 100 cells per μL, and 587 (23%) had severe anaemia (haemoglobin <8 g/dL)." (PMID 30032978, 2018). "Screening for anemia in this population would be a useful strategy; especially for female patients, those who are underweight and have a low CD4 cell counts." (PMID 29334932, 2018). "The odds of developing anemia were 3 times higher among HIV infected individuals with CD4 count of < 200 cell/ul compared with HIV infected individuals with CD4 count is > = 200/ul [(OR = 3.01 (95% CI: 1.87, 4.84))]." (PMID 30459953, 2018). "Year and age at ART initiation, sex, nationality, baseline CD4 count, anaemia, body mass index and initiating regimen were predictors of ten‐year attrition." (PMID 30318848, 2018). "Anemia, baseline CD4 count or percent below the threshold, advanced WHO HIV clinical disease staging (III and IV), severe stunting, and severe wasting were found to be independent predictors of mortality among HIV children on ART." (PMID 29482600, 2018). "Low CD4 count, WHO clinical stage III&IV, OIs and low level of BMI were found to have significant association with the occurrence of anemia." (PMID 30459953, 2018). "There should also be strict and frequent monitoring of HIV infected individuals CD4 count than previous in order to minimize anemia and related burdens." (PMID 30459953, 2018). "This study confirms that anemia is directly related with the degree of immunosuppression, a finding that agrees with those found by others; the lower the CD4 count the higher the prevalence of anemia." (PMID 29632668, 2018). "B6.Rag2−/− mice receiving CD4+ T cells displayed anemia similar to wild type immunocompetent mice, as measured by both erythrocyte count and hematocrit." (PMID 30619317, 2018). "We found that, the prevalence of anemia was increased with decreasing CD4 count both before and after ART initiation with a high prevalence among patients with CD4 count < 200 cells/mm3." (PMID 29568529, 2018). "Severe anemia, low CD4 count, and WHO clinical stage were predictor of TB incidence in HIV patients." (PMID 28451539, 2017). "Comparing the clinical phenotype of patients with confirmed TB stratified according to urine-LAM status revealed that those testing LAM-positive had lower CD4 cell counts and a higher prevalence and severity of anaemia." (PMID 28320384, 2017). "In regression analysis, low CD4 cell count, anemia, and WHO clinical stage were independent predictors of TB incidence in HIV patients receiving ART." (PMID 28451539, 2017). "We explored established risk factors for immune reconstitution inflammatory syndrome (IRIS), such as anemia, low CD4+ count, and a drop in HIV RNA load." (PMID 28931222, 2017). "Based on baseline CD4 count, there was a significant difference in the prevalence of anemia within the three CD4 categories." (PMID 28116101, 2017). "In multivariable analysis, the only independent predictors of a positive urine-LAM status among confirmed TB patients (n = 136) were lower CD4 cell counts and more severe anaemia." (PMID 28320384, 2017). "The prevalence of overall anemia increased with decreasing CD4 count, with 48.5% among patients with CD4 count < 200 cells/mm3, and 30.9 and 12.3% among those with CD4 count of 200–350 and >350 cells/mm3 respectively (P < 0.001)." (PMID 28116101, 2017). "Patients were largely excluded on the basis of laboratory tests, mostly due to: hepatitis B positive, CD4 count >350 cells/μL, elevated creatinine clearance, anaemia, thrombocytopaenia, and elevated AST/ALT level." (PMID 28832288, 2017). "Resident (AOR: 4.67; 95% CI: 1.44, 15.14), malaria infection (AOR: 2.42; 95% CI: 1.16, 5.04) and CD4 + count were predictors for anemia." (PMID 28184306, 2017). "CD4+ or CD8+ T-cell-depleted mice developed severe anemia and eventually died 2 to 3 weeks postinfection." (PMID 28396319, 2017).
anemia (continued). "Abnormal CD4 cells count and anemia were common in treatment-naïve HIV subjects who have dyslipidemia." (PMID 29610642, 2017). "There is a need for clinicians to routinely evaluate HIV subjects for dyslipidemia and further search for anemia and low CD4 cells count in those who have dyslipidemia in the early stage." (PMID 29610642, 2017). "Fibrosis progression was associated with male gender (P = 0.01), older age (P = 0.001), from low/moderate HBV-endemic country (P = 0.007), lower nadir CD4+ cell count (P = 0.03), higher fasting glycaemia (P = 0.03) and anaemia (P = 0.004) at TDF-initiation." (PMID 28362068, 2017). "There is a need for clinicians to routinely evaluate HIV subjects for dyslipidemia and further search for anemia and low CD4 cells count in those who have dyslipidemia in the early stage of the infection." (PMID 29610642, 2017). "This study recorded a high prevalence of anaemia in the HIV-infected children who had lower CD4 T cell counts as well as those at clinical stage IV." (PMID 27682438, 2016). "In our study patients with low baseline CD4 count (<200cells/μl) were 2.27 times more likely to have anemia than those with CD4 count of more than 200cell/μl at baseline (OR=2.27, P=0.003)." (PMID 27200131, 2016). "Both low CD4 counts and advanced WHO stage signify HIV disease progression a state which has been associated with increased risk of anemia." (PMID 27200131, 2016). "Hb, iron, ferritin, and TSAT decreased from grade 1 to grade 3 anaemia and CD4/CD3 lymphocyte count was lowest in grade 3 anaemia (P < 0.05)." (PMID 27092270, 2016). "On bivariate analysis, the hazard of attrition was higher among patients who were male, aged >45 years, not married, illiterate, in WHO clinical Stage 3 or 4, had a CD4 count of less than 200 cell/μL, had BMI <25 kg/m2, and had anaemia." (PMID 27562473, 2016). "Male sex (HR 1.5, 95% CI 1.4–1.6), WHO clinical Stage 3 and 4, CD4 count <200 cells/μL, abnormal BMI, and anaemia were statistically significant predictors of attrition." (PMID 27562473, 2016). "Geometric mean parasite density (GMPD) was significantly higher (3098.4, P = 0.02) in children who presented with fever, had CD4 T cells ≥500 cells/μL (491.3, P = 0.003) and those with moderate anaemia (1658.8, P = 0.03) than their respective counterparts." (PMID 27682438, 2016). "Investigations suggested mild anaemia, elevated erythrocyte sedimentation rate, deranged liver function tests, Mantoux test of 25 mm and CD4 count of 417 cells μl-1." (PMID 30459978, 2016). "Albumin levels < 3.5 g/dl were increasingly more frequent across higher grades of anemia and lower CD4 counts." (PMID 26825478, 2015). "These include anemia, hypoalbuminemia, low body mass index (BMI), low baseline CD4+ T cell count, and clinical disease stage." (PMID 25719208, 2015). "There was a significant increase in severity and prevalence of anemia in those with CD4+ T cell counts below 350 cells/μL (P < 0.05)." (PMID 25878898, 2015). "Prevalences of anemia were 81% in men, 76% in women, and 68%, 73%, and 89% in participants with CD4 cell counts of >500, 200–500, and <200 cells/μL, respectively." (PMID 25904736, 2015). "The aim of the study was to determine the prevalence of intestinal parasites in relation to CD4+ T cells levels and anemia among HAART initiated and HAART naïve pediatric HIV patients in a Model ART center in Addis Ababa, Ethiopia." (PMID 25658626, 2015). "Anemia has been reported as a prevalent condition in HIV infected children, and it has also been associated with age, CD4 count and clinical or immunological status." (PMID 25881135, 2015). "TB incidence rates were 2.5-fold higher in patients with severe anaemia compared to incidence rates in patients with CD4 counts <100 cells/uL." (PMID 25889688, 2015). "Low CD4+ T cell count, underweight, and anemia are known predictors of such outcomes but are highly prevalent among people starting ART." (PMID 25719208, 2015).
anemia (continued). "Severe anemia (grade III/IV) was a significant risk factor for 10-week mortality following adjustment for the baseline Hb level, CD4 count, fungal burden, altered mental status, and study (aOR, 2.2; 95% CI, 1.1 to 4.3; P = 0.028)." (PMID 26349818, 2015). "All 13 adult patients presented with very low CD4+ T-cell counts, anaemia and widespread skin lesions." (PMID 29568581, 2015). "Although HAART has the capability of reducing the incidence of anemia and lymphopenia by suppressing viral replication and increases CD4 cell count, anemia remains a common problem even for patients treated with antiretroviral agents." (PMID 26413303, 2015). "There has been a decline in the prevalence of anaemia and an increment in mean CD4+ T cell count among HIV infected patients after ART initiation, as seen from studies carried out in Africa, such as Adane’s study." (PMID 26474481, 2015). "After 12 months of HAART, low CD4 count was a predictor of anemia suggesting poor recovery and probably high viral load in those patient with anemia after 12 months of HAART." (PMID 26045966, 2015). "Early diagnosis of HIV, nutritional support, proper investigation and treatment for patients with low CD4 counts and for those presenting with anaemia are crucial issues towards improvement of HIV program outcomes in resource-limited settings." (PMID 25268903, 2014). "The prevalence of anemia was significantly higher (34.5%, P = 0.011) in patients with CD4 count < 200/μl." (PMID 24666771, 2014). "Anaemia was more common among women with a CD4<200 receiving ZDV (75.9%) or triple ARV (91.2%) as compared to women with a CD4>200 receiving ZDV (61.3%) or triple ARV (60.2%)." (PMID 25222119, 2014). "In conclusion, anaemia was most common among women in the advanced stage of HIV infection (CD4<200 cells/mm3)." (PMID 25222119, 2014). "There was a decline in the prevalence of anemia and increment of mean CD4+ T cell count among HIV infected patients after HAART initiation." (PMID 25335859, 2014). "Compared with female ART enrollees, males had a higher median weight (57 kg vs. 50 kg, p<0.001) and a lower prevalence of severe anemia (HB <8 g/dL) (10% vs. 16%, p<0.001), but also a lower median CD4 count (119/μL vs. 146/μL, p<0.001)." (PMID 24866468, 2014). "The subjects who were on WHO clinical stage III or IV were 3 times more likely to have anaemia as compared with those in the WHO clinical stage I. Similarly, the prevalence of anaemia increased as the CD4 Count decreases among the subjects." (PMID 24761799, 2014). "Our overall mortality for both levels of care was lower compared to similar cohorts in SSA, but the risk factors for death were similar to other cohorts from the countries most affected by HIV; these are male sex, anemia, and low baseline CD4 count." (PMID 25028610, 2014). "Significant haemoglobin recovery occurred regardless of prevalent and/or incident TB, gender, AZT exposure, baseline anaemia severity, CD4 cell count and HIV viral load measurements." (PMID 25528467, 2014). "HIV patients with CD4 cell count <200 cells/μl before HAART initiation had higher prevalence of anemia (35.2%, P =0.001)." (PMID 25335859, 2014). "There was a decline in the prevalence of anemia and increment of mean CD4 cell count among HIV infected patients after HAART initiation." (PMID 25335859, 2014). "Decompensated liver disease, CAD, CKD, and anemia were associated with increased risk of mortality among individuals with HIV/HCV coinfection, while higher CD4 count and HCV treatment were associated with lower risk of mortality in this group." (PMID 25006471, 2014). "Mortality was higher when the CD4 count was low (HR = 5.3; CI 95%: 3.2-9.0; p = 0.000), in those with anemia (HR = 3.0; CI 95%: 1.6-5.6; p = 0.001) and with abnormal chest X-rays (HR = 2.4; CI 95%: 1.4-4.0; p = 0.001)." (PMID 24679187, 2014).
anemia (continued). "Anemia is observed in both antiretroviral therapy treated and untreated individuals, but severity varies due to the immune status or CD4 cell levels and also the prevalence increases as the disease advanced and left untreated." (PMID 25335859, 2014). "Clinical presentation in affected patients usually includes fever, diarrhea, weight loss, abdominal pain, swelling of lymph nodes, hepatosplenomegaly, progressive anemia, low CD4 lymphocyte count, and sometimes hyperammonemia." (PMID 24693456, 2014). "Significant improvements in haemoglobin levels and corresponding resolution of anaemia was observed during the first year of ART, irrespective of TB disease status, gender, AZT exposure, baseline anaemia severity, baseline CD4 count or baseline HIV viral load." (PMID 25528467, 2014). "If an individual used antiretroviral treatment effectively, there will be an increased level of CD4 cells and hemoglobin concentration, which in turn decrease the occurrence of anemia." (PMID 25335859, 2014). "Decompensated liver disease, CAD, CKD, and anemia were associated with materially increased risk of mortality among individuals with HIV/HCV coinfection, while higher CD4 count and HCV treatment were associated with lower risk of mortality in this group." (PMID 25006471, 2014). "Female sex and high CD4 counts >250mm3 were predictors of ADRs whereas females were significantly more likely to develop anaemia than males." (PMID 25368714, 2014). "Higher CD4 count at ART initiation and higher BMI were associated with reduced chance of recovery from anaemia." (PMID 25722787, 2014). "Clinical and laboratory findings included anemia (67.4%), leukocytosis (90.7%), hepatosplenomegaly (60.5%), elevated liver enzymes (74.4%), decreased ratio of CD4: CD8-positive T lymphocytes (69.4%), and decreased serum IgG concentration (25.7%)." (PMID 24010978, 2013). "In conclusion, our findings showed that one-third of HAART naive HIV positive patients in Northwest Ethiopia are anaemic and the increase in prevalence of anemia with decreased CD4 cell count was statistically significant." (PMID 24238076, 2013). "The chance of developing anemia in patients with CD4 count <200 cells/μl was 9.73 times more than those with CD4 count of ≥500 cells/μl (p = 0.001, 95% CI = 2.57–36.89)." (PMID 23977253, 2013). "For example, the prevalence of anaemia was highest among patients who had a CD4 lymphocyte count of 100–199 cells/μL and lowest among patients with a CD4 count > 500 cells/μL." (PMID 24238076, 2013). "Our findings showed that one-third of HAART naïve HIV positive patients were anaemic and the increase in prevalence of anaemia with decreased CD4 cell count was statistically significant." (PMID 24238076, 2013). "In this study, the prevalence of anaemia was showed statistical significance (P<0.05) with CD4 T-cell count." (PMID 24238076, 2013). "Upon multivariable analysis, factors independently associated with clinical failure were baseline anemia (p = 0.001), CDC stage B or C (p = 0.002), and low CD4 count (p = 0.04)." (PMID 23940461, 2013). "The prevalence of mild anemia, of moderate anemia, of severe anemia increased with decreasing CD4 count (P<0.001, P<0.001, P = 0.001)." (PMID 24058490, 2013). "The overall prevalence of anemia was 14.0%, 22.4%, 50.7%, and 74.6% among patients with CD4 counts of ≥350, 200–349, 50–199, and <50 cells/mm3, respectively." (PMID 24058490, 2013). "The increase in prevalence of anaemia with decreased CD4 cell count was statistically significant (P < 0.05)." (PMID 24238076, 2013). "Additional risk factors for long term maternal mortality were not surprising, and included parameters associated with advanced disease at baseline, including lower CD4 cell counts, anemia and malnutrition." (PMID 23990966, 2013). "That study revealed a significant increase in the number of cases of anemia with decreasing CD4 counts." (PMID 24058490, 2013).